ARID1A (AT-rich interaction domain 1A)
Diseases named in the same sentence as ARID1A in open-access papers (continued):
Sharing a sentence is not in itself a finding about the gene and the disease.
endometrioid carcinomas (continued). "Ovarian clear cell and endometrioid carcinomas frequently carry ARID1A mutations but none of the high grade ovarian serous carcinomas have mutation in ARID1A." (PMID 23502471, 2013). "In 3 out of the 6 OEM from iPAD mice, Pax8-positive cells in OEM partially lacked the expression of both Pten and Arid1a and showed cellular stratification, a cribriform structure, and stromal invasion with prominent nuclear atypia, corresponding to endometrioid carcinoma." (PMID 37221199, 2023).
pancreatic cancer (60 papers, 2012 to 2026). "We found increased infiltration of various immune cells including T cells, granulocytes, neutrophils and B cells in the KAR tumours, consisting with the finding that ARID1A‐mutated pancreatic cancer patients are more responsive to immune checkpoint blockade." (PMID 40621620, 2025). "We next used a pancreatic cancer patient cohort (n = 102) collected in our hospital to test the association between ARID1A and FASN with clinicopathological features of patients." (PMID 40621620, 2025). "Collectively, our study elucidates a novel mechanism by which ARID1A loss contributes to the development of pancreatic cancer and clarify the distinct features in the microenvironment of pancreatic tumours with different genetic alterations." (PMID 40621620, 2025). "Our findings demonstrate a clear genetic dosage effect of ARID1A loss in pancreatic cancer, as homozygous deletion (KARL/L) led to more aggressive tumour progression and shorter survival compared to heterozygous deletion (KARL/+)." (PMID 40621620, 2025). "Third, activation of the PI3K/AKT signalling was frequently observed in pancreatic cancer cells with ARID1A loss." (PMID 40621620, 2025). "Because mutations are more frequently found than downregulation in the ARID1A gene in pancreatic cancer, the association needs to be re‐examined after checking the mutation status of ARID1A gene in the patients." (PMID 40621620, 2025). "A similar effect was observed in the MIAPaCa‐2 and AsPC1 human pancreatic cancer cell lines, which carry ARID1A mutations or exhibit low ARID1A expression." (PMID 40621620, 2025). "The application of TVB2640 in the treatment of ARID1A‐deficient pancreatic cancer patients warrant further investigation." (PMID 40621620, 2025). "FASN is a potential therapeutic target for ARID1A‐deficient pancreatic cancer.Mutations in AT‐rich interactive domain‐containing protein 1A (ARID1A) gene are frequently found in pancreatic cancer." (PMID 40621620, 2025). "Inhibition of FASN by siRNA also suppressed the growth of mouse (KAR#1 and KAR#2) and human (BxPC3) pancreatic cancer cells with ARID1A loss." (PMID 40621620, 2025). "Pancreatic Cancer: Recent comprehensive sequencing analyses of pancreatic cancer have demonstrated ARID1A mutations in 6% of cases." (PMID 38893181, 2024). "Mutations in ARID1A have been identified in various gastrointestinal cancers, including colorectal, gastric, and pancreatic cancers." (PMID 38893181, 2024). "When combined with KRAS activation, loss of ARID1A in the pancreas accelerated the formation of intraductal pancreatic mucinous neoplasms (IPMNs) and pancreatic cancer." (PMID 36999792, 2023). "The 24 pancreatic cancer genomes with ARID1A mutations showed a significant increase in mutation frequency at TSSs (FDR = 1.7 × 10− 7, FC = 1.27)." (PMID 33941236, 2021). "Candidate drivers of localised mutagenesis are also apparent: BRAF mutations associate with mutational enrichments at CTCF binding sites in melanoma, and ARID1A mutations with TSS-specific mutagenesis in pancreatic cancer." (PMID 33941236, 2021). "For instance, ARID1A copy number loss is the major cause of low ARID1A expression in pancreatic cancer (47%)." (PMID 32334542, 2020). "Previous studies showed that copy number loss in ARID1A was the major mechanism for loss of expression in pancreatic cancer." (PMID 32334542, 2020). "Inhibition of PI3K/AKT signals has been shown to radio-sensitizes pancreatic cancer cells with ARID1A deficiency in vitro." (PMID 31731647, 2019). "ARID1A nonsense/missense mutations have been reported in tumors from patients with pancreatic cancer, and an in vitro or in vivo loss of ARID1A expression in the pancreas is associated with reduced SOX9 expression and cancer cell differentiation." (PMID 31238554, 2019).
pancreatic cancer (continued). "ARID1A expression in the tumor of patients with pancreatic cancer decreased, and decreased ARID1A expression is associated with tumor stage/grade, lymphatic invasion/metastasis, and poor prognosis." (PMID 31238554, 2019). "By contrast, in pancreatic cancer - where ARID1A mutations and loss of expression are also common - in vitro knockdown led to divergent effects depending on the cell type used, including reduced cell proliferation as shown here for RT112 cells." (PMID 23650517, 2013). "47% of pancreatic cancer tissues show ARID1A gene copy number loss, which is the main reason for low expression." (PMID 23349767, 2013). "Our data suggested that FASN overexpression induced by ARID1A loss may promote ERK activity to stimulate the proliferation of pancreatic cancer cells." (PMID 40621620, 2025). "In addition, PI3K/AKT inhibitors have been shown to enhance radiosensitivity of ARID1A‐deficienct pancreatic cancer cells." (PMID 40621620, 2025). "Moreover, FASN expression is highly expressed in ARID1A‐low tumours and is associated with worse survival in pancreatic cancer patients." (PMID 40621620, 2025). "In this study, we identified a new therapeutic target FASN in ARID1A‐deficient pancreatic cancer." (PMID 40621620, 2025). "In addition to mutation, loss of ARID1A expression is associated with worse clinical outcomes in different cancers including pancreatic cancer." (PMID 40621620, 2025). "In addition, ARID1A loss increased cyclin D1 expression in another pancreatic tumor cell line experiment." (PMID 37109525, 2023). "We further show that the deletion of the human ARID1A pancreatic enhancer impairs ARID1A expression, defining a locus for non-coding mutations that may increase the risk for pancreatic cancer." (PMID 35410466, 2022). "On tissue NGS of immunotherapy-treated, SWI/SNF-altered pancreatic cancer patients, 7 patients harbored an ARID1A alteration (77%); 2 harbored an ARID1B mutation (22%); 3 harbored a SMARCA4 mutation (33%); 1 harbored a SMARCB1 mutation (11%); and 1 harbored a PBRM1 mutation (11%)." (PMID 34375311, 2021). "Besides novel understanding of context-dependent role of Arid1a in pancreatic cancer, this study will also enable development of therapeutic strategies for pancreatic cancers patients with ARID1A mutations, which is currently a critical unmet need in clinic." (PMID 32967217, 2020). "The application of the concept of synthetic lethality has initiated several studies combining inhibitors of PARP (olaparib) with PI3K inhibitor (BKM120), testing PI3K-inhibitor LY294002 or AKT-inhibitor MK2206 in ARID1A mutated radio-resistant pancreatic cancer." (PMID 31731647, 2019). "Removing Arid1a in mice embryos at the same time as activating the Kras mutation did not have the same effect: as the Kras mutation alone eventually leads to formation of pancreatic cancer." (PMID 30014853, 2018). "ARID1a mutations are present in six percent of pancreatic cancers." (PMID 25714017, 2015). "Finally, we found an enriched fatty acid metabolic pathway in the KAR tumours and identified a druggable target in the pathway which could be helpful for the treatment of ARID1A‐deficient pancreatic cancer." (PMID 40621620, 2025). "Moreover, we identify FASN as a new therapeutic target in ARID1A‐deficient pancreatic cancer." (PMID 40621620, 2025). "To understand how Arid1a deletion and K‐ras mutation uniquely shape tumour characteristics, we compared KAR tumours to the well‐established KPC model of pancreatic cancer." (PMID 40621620, 2025). "In order to investigate the role of Arid1a in pancreatic cancer progression, we analysed both genetic and phenotypic features in mouse models with targeted deletions of Arid1a." (PMID 40621620, 2025). "When activated K‐ras gene was introduced into the Arid1a‐depleted mice, all three studies showed the development of pancreatic tumours in the mice." (PMID 40621620, 2025).
pancreatic cancer (continued). "Collectively, ARID1A deficiency upregulates fatty acid metabolism to accelerate pancreatic tumourigenesis and FASN is a potential therapeutic target for ARID1A‐deficient pancreatic cancer." (PMID 40621620, 2025). "In this study, we established a mouse model with K‐ras mutation and Arid1a depletion (KAR mice) in the pancreas and showed that the combination of these two genetic alterations induced pancreatic tumour formation." (PMID 40621620, 2025). "Mutations in the AT‐rich interactive domain‐containing protein 1A (ARID1A) gene are frequently found in pancreatic cancer." (PMID 40621620, 2025). "An additional study of AZD6738 investigates solid tumors (including pancreatic cancer) and determines response rates to therapy with ATR kinase inhibitor monotherapy and in combination with olaparib in an ATM loss and an ARID1A mutated subgroup (NCT03682289)." (PMID 38184614, 2024). "This context-dependent role of ARID1A is also seen in other cancers, such as lymphoma, colon cancer, bladder cancer, pancreatic cancer and liver cancer." (PMID 36980292, 2023). "A previous study showed that ARID1A knockdown leads to decreased CDKN2A expression with subsequently increased cell proliferation in a KRAS-mutant pancreatic cancer cell line." (PMID 37109525, 2023). "These genetically engineered mouse model (GEMM) data, plus the high prevalence of ARID1A/RNF43 mutations in our cohort and other PDAC cohorts, established that these two genes were bona fide tumor suppressor genes for pancreatic cancer." (PMID 36999792, 2023). "And the ARID1A variation ratio was identified in about 10–20% of hepatobiliary and pancreatic cancers." (PMID 34249744, 2021). "Pancreatic cancer genomic characterization through TCGA found SWI/SNF alterations in 10% of samples (ARID1A, 6%; PBRM1, 4%)." (PMID 34375311, 2021). "It was reported that ARID1A variations were present in 18.7% of gastric, 13.7% of hepatocellular, 9.4% of colorectal, and 3.6% of pancreatic cancers." (PMID 34249744, 2021). "To understand the functional role of Arid1a in development of pancreatic cancer, we generated LSL-KrasG12D; Arid1afl/fl; Ptf1a-Cre (“KAC”) mice by crossing Arid1afl/fl; Ptf1a-Cre (“AC”) mice with Lox-stop-lox KrasG12D mice." (PMID 32967217, 2020). "We aim to understand the role of Arid1a in pancreatic cancer development and maintenance by investigating its role in both early pancreatic precursor cells and established pancreatic cancer cells." (PMID 32967217, 2020). "In the present review, we summarized the mutations of epigenetic regulators, including ARID1A, SMARCA2, SMARCA4, KDM6A, KMT2C, KMT2D, and BRD4 in GI cancers—in particular, pancreatic cancer—and found these regulators to be frequently mutated." (PMID 31238554, 2019). "ARID1A-deficient pancreatic cancer cells are selectively sensitive to ARID1B knockdown and have lower viability compared to ARID1A-expressing cells." (PMID 31769422, 2019). "In this study, we used a rapid and robust mouse-modeling platform to study the consequences of inducible and reversible suppression of the Arid1a SWI/SNF subunit in a mouse model of pancreatic cancer." (PMID 30014851, 2018). "Suppression of Arid1a in adult acinar cells harboring oncogenic Kras mutations accelerates acinar to ductal reprogramming and specification of mucinous, pancreatic cancer precursor lesions that cannot be reversed by restoring endogenous Arid1a expression." (PMID 30014851, 2018). "Putative DNA binding subunits ARID1A, ARID1B, and PBRM1, enzymatic subunits SMARCA2 and SMARCA4, and ARID2 have been shown to be mutated in pancreatic cancer." (PMID 27999365, 2016). "In pancreatic cancer, recent whole genomic sequencing also revealed pathogenic mutations and structural variants in several epigenetic regulator genes including KDM6A, ARID1A, ARID1B, PBRM1, SMARCA2, SMARCA4, and MLL2." (PMID 27999365, 2016).
pancreatic cancer (continued). "ARID1A, ARID1B, PBRM1, SMARCA2, and SMARCA4 are all components of the SWI/SNF complexes, and were shown by genomic sequencing studies to be mutated in pancreatic cancer." (PMID 27999365, 2016). "Additionally, Arid1a overexpression significantly reduced the activity of extracellular signal‐regulated kinases (ERKs) in both mouse and human pancreatic cancer cells, while p38 kinase activity remained unchanged." (PMID 40621620, 2025). "However, a paradoxical role of Arid1a in restraining the growth of pancreatic cancer cells in vitro and in vivo has also been reported." (PMID 40621620, 2025). "However, despite this relatively low frequency of genetic alterations, three independent studies of ARID1A protein abundance in pancreatic cancer tissue samples have reported lost or reduced ARID1A expression in 26%, 36%, and 51% of cases." (PMID 40723241, 2025). "Interestingly, only 13% of the KARhet mice developed pancreatic tumour at the same age, suggesting a dosage‐dependent effect of Arid1a in inhibiting tumourigenesis." (PMID 40621620, 2025). "In addition, inhibition of FASN by chemical inhibitors or siRNA knockdown attenuated ERK activation and proliferation in ARID1A‐defecient pancreatic cancer cells." (PMID 40621620, 2025). "However, the knockout of the ARID1A subunit of the SWI/SNF complex can lead to gemcitabine resistance in pancreatic cancer cells." (PMID 39609317, 2024). "These pancreatic tumours may have ARID1A gene alterations, similar to TCGA patient data showing the low frequency of gene mutations or deep deletions." (PMID 35393414, 2022). "Interestingly, we observed a replicative advantage of VSV∆51-amiR-4 in ARID1A-expressing pancreatic cancer patient-derived samples using our unique biobank of pancreatic cancer patient-derived xenografts." (PMID 35393414, 2022). "In pancreatic cancer, recent studies have shown that ARID1A is necessary to maintain terminal differentiation of pancreatic acinar cells, and knockout of ARID1A results in the accelerated formation of acinar-to-ductal metaplasia (ADM) and then pancreatic intraepithelial neoplasia (PanIN) lesions." (PMID 33983114, 2021). "The nonimmunotherapy-treated SWI/SNF-altered pancreatic cancer patients harbored 5 ARID1A alterations (83%) and 1 SMARCA4 mutation (17%); none possessed more than 1 SWI/SNF complex alteration." (PMID 34375311, 2021). "Despite recurrent mutations in ARID1A in genomes of human cancer, including pancreatic cancer, its role in tumorigenesis is not clear." (PMID 32967217, 2020). "ARID1A dysregulation plays an important role in GI cancers other than pancreatic cancer." (PMID 31238554, 2019). "In a pancreatic cancer model, Arid1a was shown to have very context-dependent roles." (PMID 31217031, 2019). "Similar to ARID1A, SMARCA4 is highly mutated in pancreatic cancer." (PMID 31238554, 2019). "Importantly, the AT-rich interactive domain 1A (ARID1A) gene which encodes the BAF250a protein, is the most frequently mutated of the SWI/SNF subunit, and has been reported to be mutated in nearly 20%–23% of pancreatic cancer cases." (PMID 31480737, 2019). "Now, in eLife, Scott Lowe and colleagues from the Memorial Sloan Kettering Cancer Center, the Hannover Medical School and the University of Michigan – including Geulah Livshits as first author – report how a subunit of SWI/SNF, called Arid1a, is involved in the development of pancreatic cancer." (PMID 30014853, 2018). "FGFR3 and ARID1A mutations may represent actionable targets in TACSTD2-high urothelial cancer, while KRAS mutations may be an attractive target for TACSTD2-high CRC and pancreatic cancer." (PMID 38986529, 2024).
pancreatic cancer (continued). "The role of chromatin remodeling in pancreatic cancer has been heavily investigated as several genes involved in histone methylation (MLL2 and MLL3) and members of the tumor suppressing SWI/SNF complex (SMARCA1 and ARID1A) are recurrently mutated in PDAC tumors." (PMID 34049503, 2021). "Thus, while the ability of Arid1a to stabilize acinar cell identity may act as a barrier to pancreatic cancer initiation, other factors are likely necessary to promote the PanIN-to-PDAC transition." (PMID 30014851, 2018). "To determine whether the same might extend to other SWI/SNF subunits that we observed to be commonly mutated or deleted in pancreatic cancers, we used RNAi to knockdown SMARCA2 (the alternative enzymatic subunit), ARID1A or ARID1B (DNA targeting/specificity subunits) in normal HPDE cells." (PMID 29515757, 2018). "The previous reports, together with this study, indicate that PBRM1, ARID1A, and SMARCB1 play tumor-suppressive roles and inhibit EMT in pancreatic cancer." (PMID 40454484, 2025). "In pancreatic cancer, genetic alterations in the SWI/SNF chromatin remodelling components including ARID1A is correlated with increased immunotherapy response." (PMID 40621620, 2025). "To confirm the clinical relevance of our findings, we analysed ARID1A and FASN expression in a pancreatic cancer cohort from The Cancer Genome Atlas (TCGA) dataset and observed a negative correlation between ARID1A and FASN expression." (PMID 40621620, 2025). "Undifferentiated pancreatic carcinomas show a higher frequency of abnormalities in SWI/SNF complex subunits, such as ARID1A and SMARCA4, and increased expression of EMT-related markers compared to ductal adenocarcinomas." (PMID 40866717, 2025). "In summary, the current analysis suggests that a subgroup of patients with pancreatic cancer and alterations in SWI/SNF complex chromatin remodeling genes, such as ARID1A, ARID1B, PBRM1, SMARCA4, and SMARCB1, can respond to ICI." (PMID 34375311, 2021). "Except for these four driver genes, more and more genes are identified as the critical genes in the process of pancreatic cancer, including ret proto-oncogene (RET), AT-rich interaction domain 1A (ARID1A), and ATM." (PMID 31552163, 2019). "Several theoretically “actionable” aberrations exist in pancreatic cancer including, but not limited to, KRAS, CDKN2A, ARID1A, BRCA, PALB2, PIK3CA, BRAF and so forth." (PMID 25714017, 2015). "Similar to ARID1A, the inactivation of RNF43 in combination with KRAS activation in the pancreas of mice significantly increased the incidence of high‐grade cystic lesions and pancreatic cancer." (PMID 36999792, 2023). "PTEN, KDM6A, and ARID1A are not established targets for successful drugs, and their evident loss of function in PDAC does not provide therapeutic strategies that are well-validated in pancreatic cancer patients." (PMID 40723241, 2025).